CA4 (carbonic anhydrase 4)
Diseases named in the same sentence as CA4 in open-access papers (continued):
Sharing a sentence is not in itself a finding about the gene and the disease.
tumor (continued). "CA-4 is a potent inhibitor of tumour cell proliferation, migration and invasion; in addition, CA-4 significantly promotes cell apoptosis, inhibits tubulin polymerisation and disrupts microtubule dynamics." (PMID 36145265, 2022). "It has been widely shown in several cancer types that the increased expression of higher antennarity N-glycans (e.g., CA3, and CA4) is correlated with cell migration, tumor progression and invasion." (PMID 35326703, 2022). "The experiments demonstrated that CA4/MTX-URPA exhibited significant inhibitory effects on tumor angiogenesis and growth." (PMID 36014696, 2022). "The disruption of tumor vasculature and the prolonged release of CA4 ensured the synergistic therapeutic effects." (PMID 35621613, 2022). "First, CA4-NPs disrupted the tumor blood vessels and led to tumor hypoxia and tumor cell necrosis, which effectively reduced tumor burden." (PMID 33897892, 2021). "The NMs can also achieve active targeting delivery of CA4 to tumor tissue by modifying targeting ligands." (PMID 34930293, 2021). "The fast release of the CA4 in tumor vessels had a synergetic effect with the slow release of DOX in tumor tissue." (PMID 34930293, 2021). "The CA4-NPs disrupted established tumor blood vessels and induced extensive tumor necrosis; however, they also increased the expression of VEGF-A and angiogenesis." (PMID 33859758, 2021). "Although the use of CA4-NPs can reduce the tumor burden in vivo, it frequently also results in high VEGF expression." (PMID 33897892, 2021). "Liu designed a GSH-responsive self-assembled nanocarrier, PEGylated poly (α-lipoic acid) copolymer, which loads CA4 through covalently linking and selectively delivered it to tumor tissues via environmental response." (PMID 34930293, 2021). "U87-MG orthotopic tumor-bearing mice treated with NGR-modified liposomes containing CA4 (NGR-SSL-CA4) had longer median survival (25 days) than mice treated with CA4-containing liposomes (SSL-CA4; 20.5 days) or CA4 alone (19 days)." (PMID 34832975, 2021). "The NP depots ensured longer-term delivery/release of CA4, which induced additional tumor hypoxia promoting nitroreductase activity and IMQ release." (PMID 33925707, 2021). "The use of CA4-NPs was aimed to cause extensive tumor necrosis mainly due to the triple target effects—EPR effect, acid-sensitive (pH = 5.5) effect to TME and good selectivity of CA4 for tumor blood vessel." (PMID 33933077, 2021). "The results showed that only the combination of triple drug-NP, or the combination of paclitaxel-NP and CA4-NP achieved a two-fold decrease in tumor slice viability." (PMID 33414428, 2021). "Liu derived a poly (L-glutamic acid)-CA4 conjugate NPs to enhance the efficacy of CA4 in tumor therapy." (PMID 34930293, 2021). "According to in vitro cellular uptake studies, significantly improved intracellular delivery of the CA-4 and increased anti-proliferation activity were obtained in angiogenic tumor endothelial cells via integrin-mediated endocytosis." (PMID 32486408, 2020). "In a MCF-7/ADR tumor xenograft model, CA4/Pasp-DOX/PEG-Phis showed superior in vivo anticancer efficacy to the controls (free DOX, free CA4, free DOX and CA4 combination, Pasp-DOX, Pasp-DOX + CA4, and CA4/DOX/PEG-Phis)." (PMID 33261219, 2020). "The combination of CA-4-NPs + plerixafor exerted a significant tumor growth and metastasis inhibition compared with monotherapies." (PMID 32486408, 2020). "A HT-29 colon tumor-bearing mousse model in an in vivo study indicated that the CA4/SN38 co-encapsulated polymeric nanoparticles displayed synergistic activities in inhibiting the tumor growth." (PMID 32630584, 2020). "The data suggested that PALA-g-mPEG/CA-4 provided the decreasing cytotoxic effect of free CA-4 and high anti-tumor activity to cancer cells with GSH sensitive release." (PMID 32486408, 2020).
tumor (continued). "The phosphate derivative of CA-4P was found to inhibit tumour blood flow at concentrations 10-fold less than its maximum tolerated dose, which led to the first clinical trial of CA-4 as a VDA." (PMID 31947889, 2020). "CA-4P nanodrugs (CA-4-NPs) were developed which exerted more vascular disrupting effect than CA-4P for strong tumor growth inhibition." (PMID 32486408, 2020). "Then, survival analysis was performed using Tumor-immune system interactionsplatform and TCGA cohort on the basis of distinct comparison expression of CA4 in five kinds of tumors." (PMID 32922550, 2020). "When “nanocells” were used in a murine tumor model, CA-4 was first released to inhibit the growth of tumor blood vessels." (PMID 32486408, 2020). "The correlation between CA4 mRNA expression and tumor immune microenvironment were analyzed in detail." (PMID 32922550, 2020). "CA-4-NPs can accumulate around tumor blood vessels and shut down tumor microvasculature but it also significantly enhanced CXCR4 expression." (PMID 32486408, 2020). "In the hyperplastic thyroid model, goiter was induced in mice and the effects of CA-4 as a tumor-specific anti-vascular agent were evaluated." (PMID 32486408, 2020). "Treatment of CA-4-NPs to the tumor tissue in mice increased the CXCR4 expression due to hypoxic conditions caused by CA-4-NPs." (PMID 32486408, 2020). "Modifications of CA-4 have produced many synthetic derivatives with extremely potent antiproliferative and anti-tumour effects." (PMID 31947889, 2020). "After accumulating at the tumor site, CA4 was released from the outer phospholipid shell of the nanocell rapidly and attacked the tumor blood vessels, and DOX was then released subsequently from the inner polymeric core for killing tumor cells directly." (PMID 31754379, 2019). "CA4 is first released to disrupt the tumor vasculature and reduce the tumor blood supply; then the impaired tumor vasculatures would promote the penetration of the drug delivery system." (PMID 31346334, 2019). "After CA-4 treatment, all tumor cells tended to become stiffer, but the Ra and Rq values exhibited diverse changes." (PMID 28628642, 2017). "Clinical studies with a more soluble phosphate derivative of CA4 (CA4P) have revealed an ability to regress tumor vasculature in a variety of cancers." (PMID 28253265, 2017). "According to the results above, F-actin was reorganized in different ways, when CA-4-stimulated tumor cells underwent G2/M arrest, apoptosis or autophygy." (PMID 28628642, 2017). "As a vascular-disrupting agent (VDA), CA-4 selectively blocks or destroys the pre-existing blood vessels in tumor tissue, leading to rapid shutdown of the blood supply in tumor tissue and subsequent killing of tumor cells via oxygen and nutrient deprivation." (PMID 28628642, 2017). "Taken together, our finding provides new insights into the mechanisms of tumor angiogenesis as well as tumor growth inhibited by CA4." (PMID 27338725, 2016). "The in vitro results of the inhibitory effect on tumor cells, the inhibitory effect on cell migration and the destructive effect on VM channels proved that CA4 has an anti-MV effect in U87-MG cells." (PMID 27283987, 2016). "The relative tumor volume of CA4 treated group was 51.6% compared to control group at the end of the 23 d therapy period." (PMID 27338725, 2016). "CA-4 class agents are highly cytotoxic against broad spectrum of human tumor cell lines including the ones that are multi drug resistant (MDR)." (PMID 27827858, 2016). "Some previous studies reported that CA4 induced regression of tumor neovessels through interference with vascular endothelial-cadherin signaling." (PMID 27338725, 2016). "As VEGF/VEGFR signaling pathway is increasingly recognized as a key regulator during tumor angiogenesis, we here investigates the effect of CA4 on VEGF/VEGFR signaling." (PMID 27338725, 2016).
tumor (continued). "Here, the observed Ktrans decrease can thus be related to the early tumor blood flow shutdown induced by CA4, as confirmed by histology." (PMID 28066252, 2016). "In summary, we have successfully synthesized a novel series of CA-4 analogues bearing a 3’-O-substituted carbonic ether moiety and evaluated their antitumor activities against four tumor cell lines using a WST-1-based cytotoxicity assay." (PMID 24304592, 2013). "A series of novel CA-4 derivatives, which contained a 3’-O-substituted carbonic ether moiety, were synthesized and evaluated for their antitumor activities against four tumor cell lines, including MDA-MB-231, MCF-7, K562 and A549 cells." (PMID 24304592, 2013). "The loading of CA4 and the targeted modification could be tuned to enhance the destruction of tumor vessels." (PMID 40343161, 2025). "Under the tumor microenvironment stimulation, CA‐4S2@ES‐Cu could release CA‐4 and ES‐Cu simultaneously." (PMID 40323152, 2025). "In response to the high GSH concentration in tumor cells, CA‐4S2@ES‐Cu could release CA‐4 and ES‐Cu, which were capable of exerting synergistic effects and striking multiple impacts on tumor cells." (PMID 40323152, 2025). "Therefore, the encapsulation of CA4 into nano-drug delivery systems for synergistic anti-tumor therapy has attracted much attention in recent years." (PMID 37176991, 2023). "In addition, the release of CA4 from the scaffold blocks blood flow into the center of the tumor tissue, resulting in the inhibition of tumor growth." (PMID 37242764, 2023). "CA4-NPs reduce tumor burden by selectively destroying established blood vessels." (PMID 37111692, 2023). "PB is activated using near-infrared radiation to strongly attack most cancer cells, and CA4 limits the energy supply; this strategy overcomes inadequate tumor growth suppression due to limited laser penetration depth and provides proof of concept for the “attack + guard” strategy." (PMID 37111692, 2023). "CA-4 can also disrupt tumor vasculature, resulting in necrosis of tumor cells." (PMID 36142133, 2022). "Immunofluorescent images of the tumors showed that CA4-NP + DC101 co-treatment could normalize tumor vasculature, enhance tumor pericyte coverage, enhance tumor blood vessel perfusion, and overcome tumor hypoxia." (PMID 36014696, 2022). "Furthermore, the effects of CA4-NPs + DC101 on reducing tumor burden and increasing the number of intratumoral immune cells were studied." (PMID 33897892, 2021). "The NMs could markedly enhance the accumulation, sustained release and cellular uptake of CA4 in tumor tissue." (PMID 34930293, 2021). "Furthermore, the effects of CA4-NPs + DC101 on reducing tumor burden and increasing the number of immune cells were studied." (PMID 33897892, 2021). "It is known that CA4 after delivered by nanoparticles in vivo could elicit central tumor necrosis and leaving normal tissues relatively impregnable, which exacerbate hypoxia in tumor tissue." (PMID 33933077, 2021). "CA4 itself has high selectivity for formed tumor blood vessels." (PMID 33933077, 2021). "CA4 as a vascular disrupting agent inhibits angiogenesis by targeting the tumor vasculature." (PMID 34832975, 2021). "The NMs could increase the tumor retention and accumulation of CA4 via EPR effect, and maintain a high level of CA4 in tumor, which led to a prolonged time of disruption and markedly improved therapeutic effect." (PMID 34930293, 2021). "Moreover, CA4 showed markedly relationship with tumor immune environment and diverse immune infiltration signatures in KIRC, LGG, LUAD and UVM." (PMID 32922550, 2020). "Prominent synergistic effects on tumor reduction were observed with RGD-modified liposomes co-encapsulating CA4 and Dox, delineating the importance of a targeted drug delivery system for the co-encapsulation of antiangiogenic and anticancer agents for cancer treatment." (PMID 32630584, 2020). "With this system, selective accumulation and release of CA-4 can occur in the tumor area." (PMID 32486408, 2020).
tumor (continued). "CA-4 appears to be specific for tumour endothelial cells, although the precise mechanism for selectivity over normal endothelial cells remains unclear." (PMID 31947889, 2020). "Thus, RGD-conjugated CA-4-loaded PEG-PLA micelles have potential as a new formulation for targeting angiogenic tumor vasculature." (PMID 32486408, 2020). "CA-platin significantly inhibited the tumor growth in the HepG2 xenograft model in vivo; however, the hybrid was less effective than cisplatin given as a single agent and cisplatin given to mice simultaneously with CA-4." (PMID 30875859, 2019). "CA-4 compounds exhibit powerful anti-tumor activity by influencing cell microtubules and changing the cytoskeleton structure; however, how these changes affect the nanostructure and nanomechanics of tumor cells are unknown." (PMID 28628642, 2017). "Using a visualized AFM technique, the goal of the present study is to investigate the alteration of nano-biophysical properties when CA-4-treated tumor cells undergo different biological processes, including microtubule depolymerization, cell cycle arrest, cell apoptosis and autophagy." (PMID 28628642, 2017). "The sensitivity of cells to CA-4 varied with the roughness and “ridge” structure of the cell surface, which may be attributed to the different sensitivities of various tumor cells to CA-4." (PMID 28628642, 2017). "Given that the ridges (or ruffles) were constantly detected only on CA-4-resistant tumor cells, we assume that the presence of “ridges” might be related to the sensitivity of cells to CA-4." (PMID 28628642, 2017). "We hypothesize that cellular nano-biophysical properties, such as the roughness and “ridge” structure, could serve as biomarkers to choose candidate tumor cells and/or predict potential mechanisms for CA-4 compounds." (PMID 28628642, 2017). "This clarification may likely help to better define the therapeutic potential and clinical indications of CA4 in treating tumor." (PMID 27338725, 2016). "Furthermore, we found that CA4 as well as CTX itself can normalize tumor vessel morphology and vessel density in the peritumoral brain area." (PMID 26831010, 2016). "CTX treatment was effective to comparable extent as CA4 in inhibiting tumor growth." (PMID 26831010, 2016). "In this work, we demonstrate that a negative modulation of tumor blood flow by CA4 treatment causes a significant decrease in gemcitabine delivery in a solid tumor mouse model." (PMID 28066252, 2016). "However, in the tumours of CIEA-NOG mice we observed a small decrease in EOC recruitment in CA4 treated mice compared to control mice, and when these mice were treated with CA4P 4 hours prior to cell administration this decrease was significant." (PMID 25466422, 2014). "We have investigated whether CA-4 functions as a tumour-specific anti-vascular agent using the hyperplastic thyroid as a novel in vivo model of neovascularization." (PMID 11259100, 2001). "These in vivo studies further demonstrated that HSPC/DSPE-mPEG2000/Cholesterol/CA4 nanoliposomes significantly reduce tumor growth when compared to free CA4 without significant weight loss in the mice, revealing excellent antitumor efficacy against breast cancer with no side effects." (PMID 40006557, 2025). "In another example, Ha and co-workers combined the chemo-drug combretastatin A-4 (CA4) with a tumor-targeting biotin portion and a PS Zn (II) phthalocyanine (ZnPc), in which a ROS-sensitive aminoacrylate linker was introduced for the controlled release of CA4 during PDT." (PMID 35890416, 2022). "Considering that CA4-NPs might induce severe hypoxic conditions resulting in high expression of HIF-1α in tumor tissues, which could induce the overexpression of PD-L1, herein we also used a programmed death-ligand 1 antibody (aPD-L1) to prevent immunosuppression." (PMID 33933077, 2021).
tumor (continued). "Furthermore, it also suggested that the sensitivity of CA-4 and its analogues to tumor cells might be differentiated by the changes in roughness and ridge structure of the cellular surface." (PMID 28628642, 2017). "In HepG2 tumor‐bearing mice, CAPL/PBAE/PLGA NMs exhibit excellent tumor‐targeting capabilities and significantly enhance the inhibitory effects of PTX and CA4 on tumor growth and angiogenesis." (PMID 41201063, 2025). "By combining treatment with CA4-NPs, FT11-TPZP-NPs achieved highly efficient enrichment and effective activation at tumor sites." (PMID 38440219, 2024). "By being combined with CA4-NPs, FT11-TPZP-NPs can accumulate in the hypoxia-aggravated tumors and activate sufficiently to kill tumor cells." (PMID 38440219, 2024). "They clarified that when the drug loading of CA4 and BLZ945 was 20.7% and the drug ratio was 0.45/1, CB-NPs showed an excellent anti-tumor effect on the H22 liver cancer model in mice and achieved a partial cure." (PMID 38375454, 2024). "The sequential delivery of CA4-NPs and MMP9-DOX-NPs increased tumor-selective drug release by amplifying MMP9 expression and enhanced antitumor efficacy with a tumor inhibition rate of 88.2%." (PMID 37415158, 2023). "The co-loading of both CA4 and DTX resulted in a significantly smallest tumor volume change compared to the control and the largest necrotic area of ~90.5%." (PMID 37102886, 2023). "CA4-NPs accumulated in tumor vessels will lead to tumor hemorrhage and coagulation reactions which enabled the circulating A15-BLZ-NPs to selectively target the CA4-NP- accumulated tumors through coagulation targeting." (PMID 37654704, 2023). "Hao developed tumor targeting peptide APRPG modified monomethoxy poly (ethylene glycol)-poly (D, L-lactide) (mPEG-PLA) self-assembled nanomicelles loaded with CA4 via hydrophobic effect." (PMID 34930293, 2021). "Carbonic anhydrase IV (CA4) inhibits the Wnt signaling pathway by targeting the WTAP-WT1-TBL1 axis and is a novel tumor suppressor in CRC." (PMID 34642262, 2021). "CA4/Pasp-DOX/PEG-Phis is first protonated and then undergoes swelling in response to tumor extracellular pH conditions (pH 6–7) in the tumor vasculature." (PMID 33261219, 2020). "In the present study, we chose three representative tumor cells (HepG2, HeLa, and MCF-7 cells) for all tests that exhibited high, moderate and low sensitivity to CA-4, respectively, according to preliminary findings." (PMID 28628642, 2017). "Excitingly, in vivo studies have revealed that CA4 is a vascular disrupting agent (VDA), which is a classification that refers to compounds that can destroy newly formed vasculature, such as found in tumour environments." (PMID 28253265, 2017). "Results demonstrated that the antiangiogenic CA4 was released from the DDS rapidly and target specifically at the tumor vasculature as soon as the DDS arrives at the tumor vasculature as guided by the iRGD." (PMID 27827858, 2016). "It was found that CA4 significantly blocked microvessels sprouting from rat aortic rings, reduced the microvessel density in CAM model and tumor tissues of MCF-7 xenograft model." (PMID 27338725, 2016). "Combretastatin A4 phosphate (CA4P), a prodrug of CA-4, and ombrabulin (AVE8062), a synthetic analog of CA4P, have been shown to suppress tumor growth by reducing tumor blood flow in different cancers in vivo." (PMID 24477603, 2014). "Mechanistically, CA-4 and eribulin both suppressed pERK signaling specifically in tumor pericytes but not endothelial cells." (PMID 40140727, 2025). "Additionally, CA‐4 was able to down‐regulate the HIF‐1α expression, restrain the neovascularization of tumors, and then interrupt the nutrient supply and restrict the tumor metastasis." (PMID 40323152, 2025). "Crucially, this study also differentiates this effect of eribulin and CA-4 from other MTAs, such as taxanes and vinca alkaloids, which do not appear to have any significant effects on tumor vasculature." (PMID 40140726, 2025).